EZH2 (enhancer of zeste 2 polycomb repressive complex 2 subunit)
Diseases named in the same sentence as EZH2 in open-access papers (continued):
Sharing a sentence is not in itself a finding about the gene and the disease.
glioma (continued). "LINC00526 inhibited glioma cell proliferation, migration and invasion via the LINC00526/EZH2/AXL/NF‐κB/LINC00526 feedback loop." (PMID 31240814, 2019). "Recent study found that PVT1 contributed to tumorigenesis of thyroid cancer through recruiting enhancer of zeste homolog 2 (EZH2), and promoting glioma vascular endothelial cell proliferation, migration, and angiogenesis by targetting miR-186." (PMID 29046366, 2017). "Although the protein levels of EZH2 and H3K27me3 were both down-regulated, GSK343 had little impact on the function of TJ905 glioma cells." (PMID 29228694, 2017). "In conclusion, the present study showed that EZH2 was a potential prognostic marker for poor OS, PFS and lower KPS score in glioma patients." (PMID 27880940, 2017). "Upregulation of miR-524-5p and miR-324-5p reduced glioma cell proliferation and increased temozolomide (TMZ) chemosensitivity by targeting EZH2." (PMID 29221202, 2017). "Meanwhile, EZH2 was shown to suppress lncRNA SPRY4-IT1 expression in the NSCLC cells, and DNMT1-mediated DNA methylation was found to lead to MEG3 silencing in gliomas." (PMID 28209205, 2017). "Therefore, we infer that PVT1 may modulate glioma cell proliferation and invasion via EZH2." (PMID 29046366, 2017). "In summary, through performing a meta-analysis, we identified EZH2 overexpression as a prognostic marker for poor OS and PFS in patients with glioma, especially in Asian patients, for WHO grade I-IV and when using IHC method." (PMID 27880940, 2017). "Due to the potent inhibition on EZH2 expression, siR-419 was chosen for subsequent studies in GL261 glioma cell lines." (PMID 29132376, 2017). "Here, we found several miRNAs repressed by EZH2, including miR-1224-3p, miR-328 and miR-214, regulate β-catenin expression by its 3′UTR in gliomas." (PMID 27385092, 2016). "The occupancy of the methylation-related histones (H3K4me2, H3K27me3, H3K9me3 and H4K20me3) on the LMO3 promoter was detected after the inhibition of EZH2, EED and DNMT3A in glioma cells." (PMID 25829251, 2015). "The responses of the three most inducible antigens, EZH2, Whsc2 and YKL-40, were reproduced in these different glioma cell lines under hypoxia." (PMID 22957023, 2012). "Both, the specific EZH2 knockdown by siRNA and the treatment with 5 μM DZNep led to a strong reduction of the trimethylation of H3K27 in human U87MG glioma cells confirming the inhibition of the EZH2 histone methylation activity." (PMID 23077658, 2012). "Hypoxic glioma cell lines increased their mRNA expression for nine TAPP (Aim2, Art-4, EphA2, EZH2, Fosl1, PTH-rP, Sox 11, Whsc2 and YKL-40), as assessed by quantitative reverse transcriptase real-time/polymerase chain reaction (qRT-PCR)." (PMID 22957023, 2012). "Another study conducted by our team on gliomas revealed that the histones corresponding to the sequences -1527bp~-1338bp and -621bp~-351bp on the PTEN promoter are the two main modification sites targeted by EZH2 (data unpublished)." (PMID 40551891, 2025). "EZH2's role in regulating GFAP expression and astrocyte differentiation is of great interest, as it may offer insights into the molecular foundation of glioma formation and potential therapeutic strategies." (PMID 40022506, 2025). "To further investigate the mechanism of CENPA in glioma, we searched for transcription factors that might bind to CENPA and found Enhancer of Zeste Homologue 2 (EZH2)." (PMID 39620895, 2024). "In addition, IHMT-337 targets EZH2 in vitro to inhibit WNK1 activation, thereby suppressing glioma migration." (PMID 38886655, 2024). "However, simultaneous overexpression of EZH2 and KCC2 rescued the promoting effect of EZH2 on glioma migration." (PMID 38886655, 2024). "Both TCGA and CGGA data revealed that the levels of EZH2 and SUZ12 are higher in high-grade glioma." (PMID 39184078, 2024). "Therefore, we believe that EZH2 can regulate the expression of SLC12A5 to activate the WNK1-OSR1-NKCC1 cascade, which controls the migration of glioma cells." (PMID 38886655, 2024).
glioma (continued). "Analysis of integrated glioma data from the TCGA database revealed a negative correlation between EZH2 and SLC12A5 expression." (PMID 38886655, 2024). "We demonstrated the crosstalk between the EZH2/H3K27me3/DNMT1 complex and AP-2α methylation in gliomas, suggesting that AP-2α methylation may be a critical epigenetic mechanism in glioblastoma." (PMID 37330579, 2023). "Gliomas with BRAF gains commonly had concomitant gains in MET, SMO, EZH2, and CDK6 (p < 0.001 each), along with other genes on 7q, which may reflect larger chromosomal duplications." (PMID 36854806, 2023). "Here, we performed rescue experiments to investigate whether the miR‐101‐3p/EZH2/VEGFA axis, involved in the lncRNA SPRY4‐IT1, promoted glioma cells proliferation and induced angiogenesis." (PMID 36479622, 2023). "USP1 in glioma, as well as USP7 and USP34, also converge on EZH2 to promote tumorigenesiss." (PMID 37892185, 2023). "To determine the clinical significance of EGFR/EZH2 dependent NFAT5 lysine methylation in glioma, we performed IHC analysis to examine the expression and correlation between EZH2 pS21 and Me3-NFAT5 K668 as well as EGFR pY1068 levels in 83 human glioma specimens." (PMID 37429858, 2023). "Finally, the EZH2/H3K27Me3/DNMT1 complex mediates the methylation modification of AP-2α gene and maintains low expression of AP-2α in gliomas." (PMID 37330579, 2023). "Furthermore, overexpressed EZH2-92aa in 293T cells and endogenous EZH2-92aa in MES28 GSCs and the murine glioma cell line GL261 were identified by mass spectrometry (MS)." (PMID 35970825, 2022). "However, the combination of EZH2 inhibitors and 10 nM of YM155 rapidly killed BE2C cells and other tested neuroblastoma cell lines NB1691 and SKNAS, and a glioma cell line SJG2, although each single agent had no obvious cytotoxicity." (PMID 36612203, 2022). "It is likely that not all DIPG or other glioma cells do exhibit the same sensitivity to EZH2 inhibitors." (PMID 35300150, 2022). "Low EZH2 immunoexpression was also observed in lower-grade gliomas (WHO grade 1 and 2), while non-neoplastic adjacent brain tissue showed complete EZH2 immunonegativity." (PMID 36292072, 2022). "Alterations of EZH2, KMT2C, and CHD4 at the genetic or protein level could perturb an epigenetic program, leading to malignant transformation in glioma." (PMID 34996478, 2022). "MiR-101 inhibits the expression of EZH2 and DNMT3A, which leads to increased levels of H3K4me3 and H4K20me3 in the core promoter region of LIM domain only 3 (LMO3), thereby inhibiting the expression of LMO3 and metastasis of glioma cells." (PMID 36497343, 2022). "• EZH2, a crux subunit of the PRC2, is a HMT enzymeresponsible for methylating lysine 27 (mono-, di-, and trimethylation)in histone H3 (H3K27) and is involved in regulation of cell stemnessand epithelial-to-mesenchymal transition (EMT) in gliomas." (PMID 35786935, 2022). "The expression profile of a public glioma dataset (CGGA) shows that the expression of EZH2 had a negative correlation with the expression of LINC00632." (PMID 36527092, 2022). "Nonetheless, the incidence, prognostic potential, and risk stratification significance of EZH2 expression in relation to IDH1 R132H protein mutant status and gliomas of various grades has not been fully elucidated." (PMID 36292072, 2022). "Indeed, treatment with DNMTi and Enhancer of zeste homolog 2 (EZH2) inhibitor was shown to upregulate NKG2D ligand expression, resulting in the lysis of glioma and HCC cells by NK cells, respectively." (PMID 33535484, 2021). "To evaluate whether FOXD2-As1 is involved in curcumol-reduced EZH2 activity, we overexpressed FOXD2-As1 in glioma cells." (PMID 34739394, 2021). "NEAT1 may interact with EZH2 and mediate H3K27 trimethylation in their promoters, and NEAT1 was essential for glioma cell proliferation and invasion, since it increased β-catenin nuclear transport while decreasing ICAT, GSK3B, and Axin2 expression." (PMID 37305396, 2021).
glioma (continued). "Also, high LI of EZH2 was a potential indicator supporting the diagnosis of higher-grade gliomas like Grades III and IV gliomas." (PMID 34745848, 2021). "However, a positive regulation of EZH2 expression by ANCR was also reported in colorectal cancer and glioma cells 59, 175, as well as osteoblast cells." (PMID 34512145, 2021). "Immunofluorescence results depicted that silencing EZH2 by lentivirus obviously reduced the expression of M2 macrophage polarization-related indicators (CD206, MIP-3α, and IL-8) but potently increased the expression of IL-6 in the glioma tissues of nude mice." (PMID 33363140, 2020). "In this study, we report that EZH2 and CXCR4 were overexpressed in glioma patients." (PMID 32635336, 2020). "These strong associations suggest that EZH2 and CXCR4 overexpression promotes tumor progression and that EZH2 and CXCR4 could possibly be used as biomarkers for a more aggressive phenotype of gliomas." (PMID 32635336, 2020). "In glioma, the functions of Enhancer of zeste homolog 2 (EZH2), which was not tested as a stem marker in this study, are closely related with stemness and mesenchymal transition." (PMID 33086625, 2020). "Furthermore, GSK126, a selective small molecule Ezh2 inhibitor that is structurally related to GSK503, has been shown to decrease levels of phosphorylated STAT3 (pSTAT3) in glioma cells that resemble stem cells." (PMID 32503684, 2020). "Given that exaggerated profiles of the MELK/EZH2/NF-κB axis are being identified in tissues with a high percentage of Ki-67+, such as the embryonic subventricular zone (SVZ) and in high-grade gliomas, it seems likely that these proteins function to promote proliferation." (PMID 31380279, 2019). "The expression of miR-133b and EZH2 in MSCs co-cultured glioma cells was detected using RT-qPCR, which showed that MSCs had no impact on miR-133b and EZH2 expression in U87 cells after the blockade of exosomes." (PMID 31842978, 2019). "Additionally, the impacts of knockdown and inhibitors on tumor burden in our work demonstrate a role of targeted therapy for glioma, which is in agreement with the previous reports aimed to alter activity of MELK/EZH2/NF-κB axis." (PMID 31380279, 2019). "We detected the expression of miR-708 and EZH2 in glioma tissues using in situ hybridization and observed a negative relationship between miR-708 and EZH2 expression, which was quantified using Spearman’s correlation analysis." (PMID 31171769, 2019). "In addition, in a study of glioma stem cells, we also found that HOTAIR can recruit and enrich EZH2 and LSD1 proteins." (PMID 29411538, 2018). "We transfected miR-524-5p mimics or miR-324-5p mimics together with and without EZH2 plasmid lacking 3′UTR into glioma cells." (PMID 29221202, 2017). "The combined results showed that EZH2 predicted poor OS and PFS in glioma patients." (PMID 27880940, 2017). "In addition, elevated EZH2 expression still had significant prognostic role for shorter OS in Asian patients, for WHO grade I-IV glioma and using IHC detection method." (PMID 27880940, 2017). "Thus, we demonstrate that in glioma cells, HOTAIR promotes cell cycle progression in an EZH2-dependent manner." (PMID 25428914, 2015). "Knock-down of ROCK1 in glioma cells did not significantly influence EZH2, EGFR, XIAP and BMI1 expression, which indicates miR-340, regulates these oncogenes through distinct mechanisms bypassing ROCK1." (PMID 25831237, 2015).
glioma (continued). "Our data indicated that the use of an unspecific DNMT inhibitor (5aza-2deoxycytidine), a DNMT1 inhibitor (procainamide) or peptides disrupting the DNMT1/PCNA, DNMT1/EZH2, DNMT1/HDAC1, DNMT1/DNMT3b and DNMT1/HP1 interactions promoted or enhanced in vivo tumorigenesis in a mouse glioma model." (PMID 23809695, 2013). "Collectively, these data indicate that EZH2 controls glioma cell invasiveness via AXL independent of DNA and histone methylation." (PMID 23077658, 2012). "5-aza failed to modulate AXL expression in glioma cells further supporting the notion that EZH2 controls AXL expression in a histone- and DNA methylation-independent fashion." (PMID 23077658, 2012). "The three most hypoxia-induced tumor antigen precursor proteins (EZH2, Whsc2 and YKL-40) were confirmed to be up-regulated at the protein level by doing immunofluorescent microscopy and intracellular flow cytometry with the glioma cell lines." (PMID 22957023, 2012). "Surprisingly, p27, p21, p16, FBXO32, EED, Cyclin E and TGF-β-1 were not induced in EZH2 knockdown cells further suggesting that EZH2 influences the motile phenotype of glioma cells independent of histone methylation." (PMID 23077658, 2012). "To investigate whether the antiinvasive effect of EZH2 knockdown is methylation-dependent, we treated U87MG glioma cells with the histone methylation inhibitor 3-Deazaneoplanocin A (DZNep)." (PMID 23077658, 2012). "Therefore, investigating the role of EZH2 in regulating GFAP expression and astrocyte differentiation may offer a deeper understanding of the molecular pathways involved in glioma development and reveal promising strategies for therapeutic intervention." (PMID 40022506, 2025). "Furthermore, immunoblotting analysis was performed to detect whether the expression of EZH2 and VEGFA are regulated by SPRY4‐IT1 in glioma cells." (PMID 36479622, 2023). "None of the WHO grade 1 gliomas exhibited high EZH2 immunoexpression." (PMID 36292072, 2022). "At first glance, these data suggest that in gliomas, ERs and EZH2 expressions are not related." (PMID 35197928, 2022). "Here, these results suggest a potential pathway by which propofol activates GABAAR, leading to the upregulation of Src and subsequent upregulation of EZH2 palmitoylation mediated by ZDHHC5 and the enhancement of stem-like properties of gliomas that may promote tumor growth." (PMID 35927718, 2022). "In glioma, HOXA11-AS could regulate the expression of EZH2 by sponging miR-214-3p." (PMID 36351895, 2022). "When Twist1 is methylated by SETD6 (a methyltransferase), it will increase the occupancy of EZH2 (a histone lysine methyltransferase) and the catalysis of the repressive H3K27Me3 (histone H3 lysine 27 trimethylation) mark at the locus of lncRNA LINC-PINT (a tumor repressor in gliomas)." (PMID 36338770, 2022). "For instance, enhancer of zeste homolog 2 (EZH2), a histone methyltransferase involved in the upregulation of c-MYC, was shown to be highly involved the tumorigenesis of GBM and decreased the survival rates, therefore representing an important prognostic factor related to the grade of the glioma." (PMID 36425564, 2022). "Nevertheless, β-catenin/USP1/EZH2 has no obvious effect on the proliferation of glioma cells." (PMID 36230759, 2022). "However, the prognostic role of EZH2 in glioma had not been exactly demonstrated prior to this study." (PMID 33277782, 2021). "Therefore, we studied on whether curcumol inhibited the development of glioma by suppressing FOXD2-AS1-mediated, EZH2-induced H3K27me3 expression in the promoter regions of anti-oncogenes." (PMID 34739394, 2021). "Therefore, we also analysed the relationship between EZH2 expression and TMB in glioma." (PMID 33277782, 2021). "We found that curcumol treatment decreased the binding ability of EZH2 to the promoter of downstream effectors (EphB3, p21, and CDKN1B) and the H3K27me3 modification in the promoter regions of effectors and increased the expression levels of effectors in glioma." (PMID 34739394, 2021).
glioma (continued). "Additionally, the upregulation of lncRNA PAR5 resulted in its binding to EZH2 and the inhibition of cell proliferation, invasion, and migration in U87 and U251 human glioma cells; notably, PAR5 expression is positively related to prognosis in glioma patients." (PMID 34202078, 2021). "Interestingly, we found that AMPK scores were significantly negatively correlated with TF expression levels in glioma: E2F4 (rho = − 0.48, P < 0.0001), EZH2 (rho = − 0.57, P < 0.0001), FOXM1 (rho = − 0.49, P < 0.0001), SMAD4 (rho = − 0.18, P < 0.0001) and SUZ12 (rho = − 0.23, P < 0.0001)." (PMID 32807122, 2020). "Consequently, this study illustrated that EZH2 induced miR-454-3p DNA methylation by binding to miR-454-3p promoter to decrease miR-454-3p expression, thus upregulating YTHDF2 and m6A decoration of PTEN, which promoted M2 macrophage polarization in glioma." (PMID 33363140, 2020). "The mechanism of its function in glioma is not fully investigated and may include EZH2-dependent epigenetic regulation, as well as regulation of β-catenin signaling and perturbed miRNA binding." (PMID 30644073, 2019). "In glioma, NEAT1 mediates the trimethylation of H3K27 in the promoter region of WNT/β-catenin pathway negatively regulated factors (Axin2, ICAT and GSK3B) by physically interacting with the PRC2 subunit EZH2 as a Scaffold, thereby resulting in WNT/β-catenin pathway activation." (PMID 29458374, 2018). "In addition, part of HOTAIR effects in glioma may also be limited by using drugs directed to PRC2 components, as the EZH2 inhibitor DZNep, or drugs that specifically target LSD1 activity and have been tested in cancer." (PMID 29644006, 2018). "Moreover, we inferred that PVT1 was an upstream regulatory gene of EZH2, and PVT1 may modulate glioma cell proliferation and invasion via EZH2." (PMID 29046366, 2017). "Thus, while EZH2 inhibition may prove beneficial in adult GBM, it will most likely be detrimental for patients with pediatric gliomas." (PMID 27449082, 2016). "However, the function of EZH2 in adults with H3K27M-mutant glioma is not very clear." (PMID 36230759, 2022). "Although shRNAs targeting EZH2 or its chemical inhibitor GSK126 significantly promoted genotoxicity and increased cell chemosensitivity, GSK126 treatments did not enhance the sensitivity of glioma cells to γ-irradiation, suggesting that the role of EZH2 could be dependent on DNA damage quality." (PMID 33859667, 2021). "Thus, we first detected the activation of EZH2 in glioma cells with or without curcumol treatment." (PMID 34739394, 2021). "Others have found that the combination of EZH2 inhibition with an HDACi is synergistic in other types of cancer; however, the effect has previously not been tested in IDH1R132H glioma." (PMID 38334611, 2024). "It has been reported that NEAT1 binding with EZH2 inhibits the transcription of the negative modulators of WNT signaling, AXIN, GSK3, and ICAT, to activate WNT signaling pathway in glioma." (PMID 38733179, 2024). "Xena Functional Genomics Explorer revealed that higher EZH2, but not EZH1, correlated to shorter survival of glioma patients." (PMID 39184078, 2024). "Here, we used Spearman's correlation analysis to evaluate the relationship between EZH2 expression and glioma MSI; however, there was no relevance between EZH2 expression and MSI in GBM." (PMID 33277782, 2021). "Even though there is no clinical application of epidrugs targeting glioma, azemetostat, a KMT6A (EZH2) inhibitor, was approved for the treatment of epithelioid sarcoma, making it the first approved histone ‘writer’ inhibitor and the first epidrug to treat solid tumors." (PMID 34168976, 2021).